AQP4 (aquaporin 4)
Diseases named in the same sentence as AQP4 in open-access papers (continued):
Sharing a sentence is not in itself a finding about the gene and the disease.
Sepsis (12 papers, 2010 to 2026). Sepsis is defined as life-threatening organ dysfunction caused by a dysregulated host response to infection. "Compared with AQP4 facilitation, pharmacological inhibition of AQP4 was associated with a more favorable clinical recovery profile, reflected by lower sepsis severity scores and a more favorable body weight trajectory during the recovery phase." (PMID 42196313, 2026). "AQP4 activity was pharmacologically modulated through either inhibition or facilitation following sepsis induction." (PMID 42196313, 2026). "In experimental models of sepsis, AQP4 deletion attenuates learning and memory impairment by reducing neuroinflammation, activating astrocytic autophagy, and downregulating proinflammatory cytokines." (PMID 39544938, 2024). "While lncRNA-5657 has not been demonstrated to regulate aquaporin expression in experimental sepsis-induced ARDS, a connection between lncRNA-5657 and AQP4 has been identified in sepsis-associated encephalopathy (SAE)." (PMID 39768394, 2024). "In contrast, AQP4 knock out mice remarkably overcame sepsis induced spatial working memory deficits as compared to the AQP4 wild‐type CLP group mice." (PMID 36922751, 2023). "To clarify the change of AQP4 in peripheral blood of SAE patients, we compared the average AQP4 concentration between the peripheral blood of healthy subjects (1.41 ± 0.56 ng mL‐1) and patients with sepsis (1.34 ± 1.16 ng mL‐1)." (PMID 36922751, 2023). "The pictographic flowchart theorizes that AQP4 aggravates sepsis‐induced neuronal injury and cognitive dysfunction by inhibiting autophagy and activating an inflammatory response in astrocytes." (PMID 36922751, 2023). "AQP3 and AQP4 have been found to promote sepsis development, with their suppression proving to be beneficial for the experimental models." (PMID 38203657, 2023). "In conclusion, AQP4 aggravates sepsis‐induced neuronal injury and cognitive dysfunction by inhibiting PPAR‐γ/mTOR‐dependent autophagy and activating inflammatory response in astrocytes." (PMID 36922751, 2023). "As such, we also investigated the possibility that sepsis can directly affect the clearance of Aβ by disrupting AQP4 distribution." (PMID 36135174, 2022). "By contrast, AQP4 expression is up-regulated during brain inflammation and aggravates brain edema in sepsis." (PMID 29449936, 2018). "As such, we wanted to identify any difference in the AQP4 distribution around Sma+ after sepsis." (PMID 36135174, 2022). "This upregulation of AQP4 can be attenuated by dexamethasone, primarily through tumour necrosis factor alpha (TNF-α) regulation, although the use of corticosteroids in sepsis remains controversial and is recommended under certain conditions." (PMID 39544938, 2024). "In sepsis, AQP1, AQP4, AQP5, and AQP9 have been shown to significantly affect organs like the brain, heart, lungs, kidneys, and liver." (PMID 39544938, 2024). "We further analyzed the area under ROC curve of disease severity score (SOFA score, APACHE II score), peripheral blood AQP4, and inflammatory factors such as TNF‐α, IL‐6, and IL‐1β of sepsis along with SAE patients." (PMID 36922751, 2023). "To verify the change of AQP4 in SAE, we analyzed peripheral blood samples from 33 SAE patients, 27 sepsis patients and 20 healthy individuals." (PMID 36922751, 2023). "Crossing target quadrant times by AQP4+/+‐sham surgery mice were significantly greater than that of AQP4+/+‐CLP mice at day 1 and day 7 post sepsis onset." (PMID 36922751, 2023). "Screening of several other autoantigens, including gastric ATPase, GAD65, AQP-4 and Ro52 also revealed high titer autoantibodies in several patients from the ARDS and severe sepsis cohorts." (PMID 20946647, 2010). "Testing for anti-AQP-4 antibodies revealed that 9% (3/35) of the ARDS and 15% (2/13) of sepsis samples had antibody titers above the cut-off value of the mean plus 3 SD of the 24 control samples." (PMID 20946647, 2010).
Sepsis (continued). "In sepsis-induced delirium (SID), increased astrocytic AQP4 expression, possibly detectable through exosomes, may serve as a biomarker for SID." (PMID 39768394, 2024). "The levels of TNF‐α in both cortex and hippocampus were elevated at day 1 post‐surgery and were dramatically decreased in AQP4 knockout mice, but not at day 7 after sepsis onset in cortical tissue." (PMID 36922751, 2023). "For example, the presence of autoantibodies against AQP-4 and GAD65 in some ARDS and sepsis patients may be related to long-term neurological deficits seen in these patients." (PMID 20946647, 2010). "Aquaporin-4 (AQP4), the predominant astrocytic water channel, plays a central role in cerebral water homeostasis, neuroinflammatory signaling, and blood-brain barrier integrity, suggesting its potential involvement in sepsis-induced cerebral dysfunction and neurorepair processes." (PMID 42196313, 2026). "In addition, AQP4 expression is upregulated in astrocytes during sepsis induced delirium (SID) and exosomes carrying AQP4 proteins from astrocytes to the peripheral blood may be utilized as biomarker for SID." (PMID 29449936, 2018).
temporal lobe epilepsy (12 papers, 2010 to 2025). A localization-related (focal) form of epilepsy characterized by recurrent seizures that arise from foci within the temporal lobe, most commonly from its mesial aspect. "In addition, AQP4 has been implicated in K+ homeostasis and regulation of excitability, and loss of perivascular AQP4 precedes chronic seizures in the kainate model of temporal lobe epilepsy." (PMID 27629271, 2017). "Furthermore, marked AQP4 downregulation has been observed in an animal model of temporal lobe epilepsy, and AQP4-deficient mice have slowed K+ kinetics and increased seizure duration." (PMID 26489685, 2015). "This study aims to examine the changes in AQP4 polarity and pericyte vascularity during temporal lobe epilepsy (TLE) progression, with the goal of identifying potential drug targets or strategies to delay the onset and progression of TLE." (PMID 41057266, 2025). "Intriguingly, they also pointed to the role of a MAPK-signaling AQP4-expression regulation pathway in temporal lobe epilepsy pathogenesis." (PMID 37569297, 2023). "AQP4 SNPS are also involved in the occurrence of the temporal lobe epilepsy, as well as schizophrenia." (PMID 36186142, 2022). "AQP4 was found to be significantly upregulated in cases of temporal lobe epilepsy (TLE) via transcriptome analysis, and mislocalization of AQP4 is implicated as a contributing factor in this condition." (PMID 32111087, 2020). "In an animal model of temporal lobe epilepsy, hippocampal AQP4 immunoreactivity was downregulated with partial recovery over time." (PMID 26489685, 2015). "Recent studies have found also changes in astroglia Kir channels and AQP4 water channels in temporal lobe epilepsy specimens." (PMID 21119878, 2010). "Transcriptomic analysis of human temporal lobe epilepsy patients showed increased AQP4 expression that may be regulated by the MAPK signaling pathway." (PMID 32397302, 2020). "When human astrocytes from patients with temporal lobe epilepsy were treated in culture with p-38 MAPK inhibitors, expression of AQP4 was downregulated." (PMID 32397302, 2020). "In the hippocampal tissue of patients with temporal lobe epilepsy (TLE), the expressions of connexin 43 and AQP4 are increased, and the expressions of the key constituents of the AQP4 multi-molecular complex (Kir4.1, a-syntrophin, and dystrophin) are downregulated." (PMID 27517922, 2016). "Nevertheless, another study reported that a significant increase in AQP4 is observed in sclerotic, but not in non-sclerotic, hippocampi obtained from patients with medically intractable temporal lobe epilepsy." (PMID 21119878, 2010).
amyotrophic lateral sclerosis (11 papers, 2012 to 2025). Amyotrophic lateral sclerosis (ALS) is a neurodegenerative disease characterized by progressive muscular paralysis reflecting degeneration of motor neurons in the primary motor cortex, corticospinal tracts, brainstem and spinal cord. "Failure of brain homeostasis maintained by glial cells has been postulated to underlie neuronal cell death in amyotrophic lateral sclerosis (ALS), and an up-regulation of AQP4 has been found in a rat model of ALS." (PMID 26526878, 2015). "The list of neurological conditions in which AQP4 might play a pathophysiological role includes epilepsy and neurodegenerative diseases, such as Alzheimer’s disease (AD), amyotrophic lateral sclerosis (ALS), Huntington’s disease (HD) and spongiform encephalopathy (SE)." (PMID 33167342, 2020). "Furthermore, aberrant up-regulation of Cx43 and AQP4 has been reported in motor neurons in a mouse model of amyotrophic lateral sclerosis (ALS) and in ALS patients." (PMID 29520011, 2018).
Anxiety (11 papers, 2016 to 2025). Intense feelings of nervousness, tension, or panic often arise in response to interpersonal stresses. "cTBS significantly attenuated the decrease in efficiency of solute clearance usually incurred with sleep deprivation, restored the loss of AQP-4 polarization and improved anxiety-like behavior in sleep-deprived animals." (PMID 39234773, 2024). "In addition, abnormalities in cerebral aquaporin‐4 (AQP4) water channel protein in PD may also represent one of the underlying reasons for the strong correlation between anxiety and glymphatic system dysfunction." (PMID 40977132, 2025). "The AQP4 inhibitor, in particular, reduced anxiety levels with measurements, well below those of both WT and untreated APPPS1 animals, and this effect was evident at both 2 and 4 weeks of treatment." (PMID 40329616, 2025). "Another study based on the MK-801 animal model found that inhibiting AQP4 can reduce the expression of inflammatory cytokines, improve anxiety-like behavior, and alleviate social dysfunction in mice." (PMID 39940642, 2025). "The AQP4 facilitator, on the other hand, improved anxiety level/memory performance at both time points, bringing these metrics closer to WT levels." (PMID 40329616, 2025). "The researchers studied the effect of cTBS on glymphatic pathway clearance in normal and in sleep- deprivation C57BL/6J mice, detecting AQP-4 polarization by immunofluorescence, and assessing anxiety-like behaviors trough open field (OF) tests." (PMID 39234773, 2024). "Sleep deprivation seems to reduce influx efficiency along the PVS, disturb AQP-4 polarization and induce anxiety-like behaviors." (PMID 39234773, 2024). "Sleep deprivation causes a reduction in influx efficiency along the perivascular space, disturbs AQP4 polarization and induces anxiety-like behaviors." (PMID 38338949, 2024). "Deletion of the AQP4 gene increased hyperactivity, intraneuronal Aβ load and glutamatergic neuron activation, but did not influence working memory or anxiety-like behaviors of 4-month-old APP/PS1 mice." (PMID 36186142, 2022).
cerebrovascular disease (11 papers, 2016 to 2025). "Ageing, cerebrovascular disease, traumatic CNS injury, and sleepdisruption are established and emerging risk factors in developingneurodegeneration, and in animal models of each, impairment of glymphaticfunction is associated with changes in perivascular AQP4 localization." (PMID 34499128, 2022). "AQP4 is the most abundant water channel in the brain and is increased during brain edema in cerebrovascular diseases." (PMID 37036005, 2023). "Regarding cerebrovascular disease, abundant evidence suggests a pivotal role for AQP4 in the formation of ischaemic brain edema, and AQP4 inhibition reduces infarct volume and improves clinical recovery in an animal model." (PMID 30563176, 2018). "Loss of AQP-4 polarization from astrocytic endfeet has been reported in cerebrovascular disorders and commonly occurs alongside an increase in AQP-4 in the parenchyma." (PMID 27374823, 2016). "In the current review, we pay more attention to the studies of recent years directly from cerebrovascular diseases animal models or patients, especially those using AQP4 gene knockout mice." (PMID 27529222, 2016). "Because brain edema is an important pathophysiological change after stoke, AQP4 is destined to have close relation with cerebrovascular diseases." (PMID 27529222, 2016). "Considering brain edema is an important pathophysiological change after stoke, AQP4 is destined to have close relation with cerebrovascular diseases." (PMID 27529222, 2016). "AQPs—especially AQP4, which is the most abundant AQP in the brain—have a key role in the formation of different cerebrovascular diseases Therefore, AQP4 is a potential target for the treatment of this kind of injury or disease, with the objective of inhibiting AQP4 expression." (PMID 30360436, 2018). "Till now, multiple studies have investigated roles of AQP4 in cerebrovascular diseases." (PMID 27529222, 2016). "Thus, a highly selective antagonist or agonist of AQP4 that can be used systemically remains to be further developed, and it promises to become a novel, effective measure of treating cerebrovascular diseases." (PMID 27529222, 2016). "This suggests that AQP4 may have a neuroprotective role in cerebrovascular disease." (PMID 35711733, 2022). "Thus, the effects of AQP4 on cerebrovascular diseases remain to be investigated, which may become the theoretical basis of AQP4 regulation treatment." (PMID 27529222, 2016).
Hyponatremia (11 papers, 2010 to 2023). An abnormally decreased sodium concentration in the blood. "In NMOSD patients, syndrome of inappropriate antidiuretic hormone secretion (SIADH) is the most common cause of hyponatremia, accounting for about 14.6%–16%.The hypothalamus is the area of high expression of AQP4." (PMID 34520629, 2021). "Water retention in combination with decreased GFR and severe hyponatremia in nephrotic syndrome and liver cirrhosis have been associated with downregulation of AQP4." (PMID 25658446, 2015). "However, she still exhibited persistent refractory hyponatremia, a positive aquaporin-4 antibodies (AQP4-Ab) result in rechecked serum, and only partial neurological improvement." (PMID 34398000, 2021). "We analyzed the pathogenesis of AQP4‐IgG positive paraneoplastic NMOSD and discussed the phenomenon of paraneoplastic NMOSD with intractable hyponatremia." (PMID 34520629, 2021). "Administration of urea or reinduction of hyponatremia during inadvertent rapid correction of hyponatremia are both known to decrease the number and severity of CPM lesions and to increase AQP4 expression." (PMID 24252214, 2013). "In young patients presenting with hyponatremia and suspected SIADH accompanied by neurological abnormalities, it is crucial to differentiate central nervous system diseases, including NMOSD, which can involve lesions in AQP4-abundant areas, such as the hypothalamus." (PMID 37904479, 2023).
colitis (10 papers, 2008 to 2025). Inflammation of the colon. "As previously reported, deficiency in AQP4 can facilitate the attenuation of experimental colitis in mouse models." (PMID 35764613, 2022). "Mice deficient in AQP4 alleviates experimental colitis, and it has been shown that there is significant difference in the microbiome of AQP4-knockout mice compared to the WT mice." (PMID 33796134, 2021). "Moreover, deficiency in AQP4 has been established to result in the amelioration of experimental colitis in mouse models." (PMID 35764613, 2022). "In addition, a genome-wide comparison of gene expression in genetically susceptible animals that develop spontaneous colitis showed that despite most upregulated genes in experimental colitis are immune-related, AQP4 and the mitochondrial ribosomal protein L33 were also strongly upregulated." (PMID 33673336, 2021). "The current study aims to investigate the mechanism of MTA1/HIF1A/AQP4 axis in experimental colitis in mice." (PMID 35764613, 2022). "For instance, AQP4 was previously identified as a significantly up-regulated gene in experimental colitis." (PMID 35764613, 2022). "Thanks to the hard-done work of our peers, the role of AQP4 in experimental colitis is well-established." (PMID 35764613, 2022). "Results of dual-luciferase reporter gene assay and ChIP assay further revealed that MTA1 activated HIF1A, and subsequently induced AQP4 transcription to up-regulate AQP4 in experimental colitis." (PMID 35764613, 2022). "Meanwhile, AQP4 promoted LPS-induced inflammation, and exacerbated apoptosis of colon epithelial cells and augmented experimental colitis development in mice." (PMID 35764613, 2022). "A murine model of colitis induced by dextran sulphate presented decreased AQP4 and AQP8 gene and protein levels that correlated with significant alteration in colonic fluid secretion." (PMID 33673336, 2021). "Aquaporin expression, especially AQP4, 7, and 8, was examined in a murine model of colitis and in patients with IBD or infection colitis." (PMID 27472320, 2016). "Chemical induction of colitis by treatment with dextran sulfate sodium results in substantial downregulation of carbonic anhydrases CA I and CA IV and aquaporins Aqp4 and Aqp8." (PMID 18680595, 2008). "Furthermore, another vital discovery was that HIF1A induced transcription of AQP4, which exacerbated the habitual occurrence of experimental colitis." (PMID 35764613, 2022). "Here, we found that the expression of AQP4 mRNA decreased significantly after 12–24 h of dextran sodium sulfate exposure and remained depressed throughout the treatment period in a mouse model of colitis." (PMID 29375520, 2017). "We then examined the effects of colitis and NLRP3 KO on astrocyte density and polarization of astrocytic AQP4 surface expression in the cortex and hippocampus as measures of astrocytic activation and function." (PMID 34229722, 2021). "In the same way, AQP4 and AQP8 are shown to decrease significantly in a mouse model of colitis after exposure to dextran sodium sulfate (DSS), confirming data obtained from clinical investigations in inflammatory bowel disease (IBD) patients." (PMID 27472320, 2016). "Altogether, MTA1 may promote AQP4 transcription by activating HIF1A, thus exacerbating DSS-induced experimental colitis in mice, which provides a novel direction for the treatment of experimental colitis." (PMID 35764613, 2022).
Hyperglycemia (10 papers, 2017 to 2025). An increased concentration of glucose in the blood. "The hyperglycemia in T2DM could cause damage to astrocytes where AQP4 is attached and could reduce AQP4, leading to reduced function of the glymphatic system." (PMID 38515515, 2024). "Other proposed mechanisms for how hyperglycemia leads to neuronal damage include the inhibition of cellular proteins such as aquaporin-4 and kallikrein." (PMID 39982264, 2025). "Fourth, the downregulation of aquaporin-4 expression in the brain induced by stress hyperglycemia can exacerbate the blood brain barrier destruction, which promotes severe vasogenic brain edema, eventually leading to worse functional outcomes after ICH." (PMID 35761206, 2022). "Results from our in vivo study suggested that hyperglycemia-induced increase in the retinal thickness was related to reactive Müller cells, as well as the fact that AQP4 channels were responsible for the edema formation." (PMID 32230876, 2020). "According to our previous study, although astrocytic AQP-4 expression was downregulated by hyperglycemia, it increased the vasogenic edema and severity of BBB destruction in ICH." (PMID 29212271, 2017). "However, hyperglycemia downregulates AQP4 expression, exacerbating cerebral edema and brain injury following ICH." (PMID 40385356, 2025). "The reduced expression of Aqp4 in hyperglycemia was further confirmed in mouse brain tissue, suggesting that hyperglycemia may disrupt the integrity of astrocyte endfeet, which are crucial for maintaining the homeostatic function of the BBB." (PMID 38802820, 2024). "A study has found that hyperglycemia could inhibit the expression of Aquaporin-4, resulting in the aggravation of vasogenic brain edema and blood–brain barrier (BBB) destruction." (PMID 38693481, 2024).